BCL2 (BCL2 apoptosis regulator)
Diseases named in the same sentence as BCL2 in open-access papers (continued):
Sharing a sentence is not in itself a finding about the gene and the disease.
prostate carcinoma (continued). "Notably, PC3 cells, the more aggressive prostate cancer model, retained an expression profile consistent with their malignant phenotype, characterized by BCL-2 overexpression, PTEN downregulation, and increased expression of the inflammation-related gene IL-6." (PMID 41465187, 2025). "In addition, CA induces apoptosis by enhancing the expression of Bax and caspase-3; and decreased expression of Bcl-2 in prostate cancer cells." (PMID 39574470, 2024). "The overexpression of Bcl-2 has been frequently observed in prostate cancer." (PMID 38535120, 2024). "Similar mechanisms targeting Bcl2 and Bax, upregulating caspase-3 pro-apoptotic gene and increasing ROS to further induce apoptosis, were noted, indicating a method to combat the proliferation of prostate cancer." (PMID 38256917, 2024). "Indeed, MYC, MCL-1, and BCL-2 are important oncoproteins in both AR-driven and AR-independent prostate cancer." (PMID 39117800, 2024). "miR-204-5p was found to promote apoptosis by downregulating Bcl-2 in prostate cancer cells." (PMID 38789509, 2024). "Moreover, downregulation of GRP94 in prostate cancer cells can cause upregulation of cleaved caspase-9 and Bax expression levels, while suppression of Bcl-2 and Vimentin expression levels can induce apoptosis and inhibition of prostate cancer cell invasion." (PMID 38649679, 2024). "The resulting CLIFI value distributions indicated heterogeneity in the expression of several proteins (MYH11, ERα, BCL2) across different cancer types (including brain glioma, breast, kidney, thyroid and prostate cancer) aligning with the original raw expression data." (PMID 39624167, 2024). "Despite the substantial downregulation of Bcl-2, prostate cancer cells may successfully develop drug resistance through other mechanisms, such as growth pathway stimulation or adaptation of the tumor microenvironment." (PMID 39501277, 2024). "The BCL2 apoptosis regulator [P10415], also validated only in one study that includes 22 patients from Qatar, is the target for 14 drugs, with ten of them used for cancer treatment and only two of them for prostate cancer." (PMID 39595075, 2024). "In addition, CA treatment on apoptotic proteins (Bcl-2, Bax, and Caspase-3) expression in prostate cancer cells was examined by western blotting." (PMID 39574470, 2024). "Additionally, Bcl-2 is critical for the survival of androgen-independent prostate cancer cells and also required for the progression of prostate cancer cells from an androgen-dependent to an androgen-independent growth stage." (PMID 36672191, 2023). "Another oncogene that plays a significant role in the progression of prostate cancer is Bcl-2." (PMID 36826044, 2023). "The reliance on PARP1 indicates the benefit BCL2-expressing prostate cancer patients may experience through PARPi therapies." (PMID 37508568, 2023). "This melatonin-induced inhibition was exemplified following a 48-hour LNCaP co-culture with hrTNF-α and melatonin, which demonstrated that melatonin promoted prostate cancer cell apoptosis through reduction of Bcl-2 as well as Survivin levels, two important carcinogenic survival factors." (PMID 37191417, 2023). "(−)-Gossypol has recently been discovered to be a powerful Bcl-2 and Bcl-xL inhibitor, which may increase the response of prostate cancer to radiation by potentiating radiation-induced apoptosis." (PMID 36559116, 2022). "Using the WGS data, we assessed the presence of variants and/or mutations in several genes that are known to be frequently mutated in prostate cancer (BRCA1, BRCA2, RB, PTEN, CDK12, PI3K, ADP-ribose, PIK3GA, PIK3CB and PIK3R1, AKT, CYP17, IGF 1, EGF, and BCL2)." (PMID 36643868, 2022).
prostate carcinoma (continued). "Another study has shown that 1alpha, 25-dihydroxyvitamin D3 (1α,25(OH)2D3) in combination with menthol might enhance the anticancer effect against prostate cancer cells via targeting the reduction of Bcl-2 protein expression and suppression of p21." (PMID 35267408, 2022). "Punicalagin and ellagic acid induce apoptosis in prostate cancer cells through some basic pathways, such as the introduction of cytochrome c in the cell cytoplasm, upregulation of Bax, and downregulation of B cell lymphoma/leukemia-2 (Bcl-2)." (PMID 35757262, 2022). "SLC25A5 promotes apoptosis through the regulation of bcl-2, caspase-3, and bax in prostate cancer." (PMID 35840882, 2022). "Furthermore, COX-2 overexpression up-regulates Bcl-2 overexpression leading to a reduction in apoptosis of prostate cancer cells." (PMID 36445555, 2022). "Therefore, BCL2 was down-regulated in prostate cancer cells treated with the most active five aplysinopsin analogs that we developed." (PMID 36615305, 2022). "Furthermore, inhibitors of BCL-2 were more effective in treating prostate cancer NE than AR-positive prostate cancer." (PMID 36643868, 2022). "Thus, ectopic BCL2 expression decreased apoptosis in prostate cancer cells and facilitated the transitioning of PCa cells to androgen-independence in vitro and in vivo." (PMID 33668112, 2021). "Likewise, pristimerin inhibited the anti-apoptotic Bcl-2 and induced apoptosis in prostate cancer cells through ROS-dependent ubiquitin-proteasomal degradation pathway." (PMID 34026649, 2021). "MJ (2 mM) inhibits Bcl-2 protein expression in vitro in the case of prostate cancer cells (PC-3)." (PMID 34068337, 2021). "In human non-small lung cancer cells (A549), MJ (A549—5 Mm; PC-3—2 mM) increases the expression of pro-apoptotic proteins from the Bcl-2, Bcl-Bax and Xs families, and in PC-3 prostate cancer cells, an increase the expression of the anti-apoptotic protein Bcl-2." (PMID 34068337, 2021). "Interestingly, BCL-2 inhibition, with venetoclax or siRNA, sensitizes taxane-resistant prostate cancer cells (PC3 and DU145) to cisplatin chemotherapy, with BCL-2 overexpression reversing this effect." (PMID 35008216, 2021). "Our findings are consistent with a previous study showing that EEOS effectively induced apoptosis in human prostate cancer cells (LNCaP) through the down-regulation of BCL-2 and significant elevation of Caspase-9 and Caspase-3 activities in a dose-dependent manner." (PMID 34440988, 2021). "Molecular mechanisms illustrated that compound 12a could induce morphological changes and affect the expression levels of apoptosis-related proteins (Bcl-2 and Cleaved-parp) against prostate cancer cells." (PMID 32299262, 2020). "Moreover, overexpression of miR-205 induced apoptosis and decreased mitochondrial membrane potential and cell growth via targeting/reducing Bcl-2 expression in prostate cancer cells." (PMID 32854238, 2020). "Evidence that Bcl-2 may have also oncogenic potential in carcinoma was first provided in prostate cancer, where high expression of the protein was found in androgen-independent tumors." (PMID 32455818, 2020). "Interestingly, increased levels of Bcl-2 are required for the progression of prostate cancer cells from an androgen-dependent to an androgen-independent growth stage." (PMID 32344908, 2020). "Moreover, in prostate cancer epithelial cells, Bcl-2-induced chloride current is mediated by ClC-3 and is associated with cell survival and cell apoptosis." (PMID 33093458, 2020). "We aimed to test whether targeting BCL2 would influence Enz sensitivity of prostate cancer (PCa) and identify the potential mechanism." (PMID 32235588, 2020). "Here we found that Enz-resistant prostate cancer (PCa) cells had higher BCL2 expression." (PMID 32235588, 2020).
prostate carcinoma (continued). "Using multiple patient datasets with expression profiles and clinicopathological information, we also found that TGF-β and higher KLF5 expression correlated with poor prostate cancer patient survival; and showed that BCL2 was a potential biomarker with both prognostic and predictive functions." (PMID 32685011, 2020). "Saffron extract (SE) showed dose and time-dependent antiproliferative effect on 5 different malignant prostate cancer cell lines (IC50 = 0.4–4 mg/mL), by arresting cells at G0/G1 phase and caused apoptosis through strikingly downregulation of Bcl-2 expression, activation of caspase-9." (PMID 31261861, 2019). "Although such relationship has been demonstrated, the existence of -κB, Bax and Bcl-2 factors in D. kotschyi needs investigation as the involvement of nuclear factor-κB, Bax, and Bcl-2 in induction of cell cycle arrest and apoptosis by apigenin in human prostate carcinoma cells." (PMID 31198431, 2019). "The protective role of Bcl-2 against apoptosis has been extensively reported in prostate cancers." (PMID 31317026, 2019). "The antiproliferative effect of carnosol on prostate cancer cell lines could be also due to inducing dysregulation of multiple signaling pathways, such as downregulation of Bcl-2 and procaspase-8 and upregulation of Bax2." (PMID 31827560, 2019). "Hence, ART exhibits anticancer properties through regulating the ceRNA crosstalk of the lncRNA UCA1/miR-184/BCL-2 axis in prostate cancer." (PMID 31178721, 2019). "Moreover, downregulation of miR-205 was inversely correlated with BCL-2 upregulation, an anti-apoptotic oncoprotein required for prostate cancer progression." (PMID 31756185, 2019). "In addition, Gln-Pro-Lys, a novel tripeptide derived from the sepia ink, has been demonstrated to exhibit anticancer properties by inducing apoptosis in Prostate Cancer cell Lines via Caspase-3 Activation and Elevation of Bax/Bcl-2 Ratio." (PMID 29649141, 2018). "Elevation in the level of the BCL2 protein has been shown to provide protection from apoptosis, and the BCL2 gene family is implicated in the development of CRPC and resistance to therapy since its expression increases during progression of prostate cancers." (PMID 30028845, 2018). "Moreover, MMSET interacts with NF-κB directly to activate the expression of NF-κB target genes (including interleukin-6, vascular endothelial growth factor A, cyclin D, Bcl-2 and Survivin) in prostate cancer cells." (PMID 29796186, 2018). "Our data revealed cellular mechanisms that may be further exploited for developing improved therapies for prostate cancer patients by retaining the Bcl-2/Beclin-1 complex for autophagy-inhibition." (PMID 29362360, 2018). "In prostate cancer, BCL2/BAX ratio is involved in modulation of radiosensitivity." (PMID 30537994, 2018). "Exosomal miR-34a could induce docetaxel sensitivity in docetaxel-resistant prostate cancer cells by inhibiting Bcl-2." (PMID 29228644, 2017). "We concluded that the role of Bcl-2 or Bcl-xL in modulation of prostate cancer cell sensitivity to combined cisplatin/LA-12 and TRAIL treatment may be cell type-specific, but not crucial in prostate cancer cell lines used within our study." (PMID 29182622, 2017). "Therefore, downregulation of BCL-2 by ursolic acid results in the apoptosis in human prostate cancer cells making the acid a suitable antiprostate cancer agent." (PMID 28286531, 2017). "Additionally, we observed also observed down regulation SOCS3 with reduced transcripts of Bcl-2 in prostate cancers cells with regards to apoptosis." (PMID 29278364, 2017). "Apigenin increased the Bax/Bcl-2 ratio in favor of cell apoptosis in prostate cancer cells." (PMID 29034071, 2017).
prostate carcinoma (continued). "Interestingly, over-expression of NR4A3/NOR1 also inhibited prostate cancer cell growth and reduced the levels of anti-apoptotic proteins BCL2 and BCL-XL49." (PMID 27586588, 2016). "Consistent with the resistance of CaP cells to clinically relevant doses of TNF-α, this cytokine was shown to increase NFκB signaling and increase expression of c-FLIP, cIAP-1 and Bcl-2, three known NFκB-regulated anti-apoptotic targets in prostate cancer cells." (PMID 26799286, 2016). "Currently several clinical trials targeting BCL2 expression in prostate cancer are ongoing; therefore CYP1A1 may be a promising target for prostate cancer treatment since it is closely associated with BCL2 expression." (PMID 27203547, 2016). "This latter result might be due to the highly significant decrease in the phosphorylation NFκB p65 in PC-3 cells since the level Bcl-2 is regulated by NFκB in prostate cancer cells." (PMID 26975752, 2016). "Numerous studies have shown that lycopene may exert its protective effect via maintaining the balance of Bax and Bcl-2 in cortical neurons, prostate cancer cells, hepatic tissue and kidney tissue." (PMID 26291709, 2015). "Our findings suggest that cyclin D1 and Bcl2 expression may be useful as predictive markers of responsiveness of prostate cancer to apigenin therapy." (PMID 26379052, 2015). "Furthermore, immunofluorescence revealed that apogossypol inhibited the growth and proliferation of prostate cancer cells by downregulating Bcl-2 protein expression and activating caspase-3 and -8." (PMID 25672487, 2015). "Evidence that BCL2 may have oncogenic potential in carcinoma was first provided in prostate cancer, where high expression of BCL2 was found in androgen-independent tumours." (PMID 26556430, 2014). "With the progress of high-throughput genomics and proteomics technology, increasing prostate cancer-related tumor markers, such as MIB-1/Ki67 labeling indices, DD3, EGR-1 and Bcl-2, are constantly being discovered and used in the diagnosis and prediction of prognosis of prostate cancer." (PMID 24959274, 2014). "In addition, formononetin from A. membranaceus induces apoptosis in prostate cancer cells via enhancing the Bax/Bcl-2 ratios and regulating the p38 phosphorylation." (PMID 25241226, 2014). "Moreover, there is experimental evidence for a correlation between a decreased metastatic potential with lowered Bcl-2 levels in prostate cancer." (PMID 24098503, 2013). "Collectively, the differential expression of BCL-2 and NOXA may cause the opposite effects of pargyline and tranylcypromine to cellular proliferation in prostate cancer cells." (PMID 23900512, 2013). "In addition, isoalantolactone triggers apoptosis in prostate cancer cells via up-regulation of Bax, down-regulation of Bcl-2, survivin, and significant activation of caspase-3." (PMID 23921797, 2013). "In human prostatic carcinoma cells, t10,c12-CLA anticancer effect associates to decreased Bcl-2 and increased p21(WAF1/Cip1) mRNA levels while in human colon or bladder cancer cells it was accompanied by the activation of ATF/NAG-1 or Insulin Growth Factor signaling." (PMID 24260504, 2013). "It is suggested that androgen-mediated mechanisms may act through Bcl-2-mediated apoptotic pathways.The overexpression of Bcl-2 in prostate cancer safeguards the tumor cells from apoptosis." (PMID 24282788, 2013). "However, recently, the hypermethylation of BCL2 gene has been reported in certain types of cancer, such as prostate cancer." (PMID 23599765, 2013). "Bcl-2 inhibitor is thus a potential treatment for prostate cancer progression or metastasis." (PMID 24349321, 2013).
prostate carcinoma (continued). "In addition, a recent study has also indicated that a natural BH3 mimetic ((−)-gossypol) induces autophagy in apoptosis-resistant prostate cancer by modulating Bcl-2-Beclin1 interaction at the endoplasmic reticulum." (PMID 22363680, 2012). "To further investigate the mechanisms of TRAIL sensitization by GSK-3 inhibition, we employed PPC-1 prostate cancer cell overexpressing Bcl-2, Bcl-XL, and Mcl-1 to inhibit the mitochondrial pathway, or cytokine response modifier A (CrmA) to inhibit the death receptor pathway of caspase activation." (PMID 22829912, 2012). "We determined whether simvastatin treatment inhibited Bcl-2-mediated cell survival pathway in prostate cancer cells." (PMID 22974127, 2012). "Overexpression of Bcl-2 has previously been reported to confer drug resistance of prostate cancers." (PMID 22347457, 2012). "Also, analysis of androgen-independent prostate cancer cells showed that gossypol interrupted Beclin 1 and Bcl-2/Bcl-xL interactions and that gossypol-induced autophagy was dependent on Beclin 1 and Atg5." (PMID 22240779, 2012). "One study showed that curcumin, a component in turmeric (Curcuma longa), could radiosensitize prostate cancer cells via the inhibition of NFκB function, which led to a downregulation of the anti-apoptotic gene Bcl-2." (PMID 21858113, 2011). "In addition, DU145 prostate carcinoma cells were demonstrated to be resistant to Fas-induced apoptosis through upregulating Bcl-2 expression." (PMID 21274285, 2011). "The down-regulation of LAMB2 and MEF2C might be involved with cell adhesion or motility in invasive prostate cancer cells and apoptosis via BCL2 transformation, respectively." (PMID 20969748, 2010). "Over-expression of BCL-2 is one of many mechanisms that may enable prostate cancer cells to survive in an androgen-deprived environment." (PMID 19646263, 2009). "The results presented in this paper show that BAD, the BH-3 only Bcl-2 protein, might function in a dual capacity in prostate cancer." (PMID 19593445, 2009). "Indeed, increased expression of anti-apoptotic Bcl-2 proteins as well as inhibitors of apoptosis proteins (IAPs) in advanced prostate cancer has been reported." (PMID 19593445, 2009). "The combined evaluation of high nuclear morphology, ploidy and cell survival parameters such as Bcl-2 expression might better identify patients with poor prognosis among early stage prostate carcinomas diagnosed by FNA biopsies." (PMID 16759347, 2006). "Indeed, in urothelial transitional cell cancer, oesophagus cancer and prostate cancer cases with Bcl-2 positivity represent poor prognosis." (PMID 14710230, 2004). "Human glioma and prostate cancer cells lost their sensitivity to TRAIL by overexpressing Bcl-2." (PMID 12644829, 2003). "Elevated levels of bcl-2 protein may contribute to the progression of prostate cancers to a metastatic and hormone-insensitive state characterized by poor responses to chemotherapy." (PMID 11500787, 2001). "Following this, the expression levels of apoptosis-related genes (BAX, Bcl-2), an angiogenesis gene (VEGF-C), a gene associated with progression and development (HIF-1α), genes involved in the EMT pathway (SNAIL and E-Cadherin), and a prostate cancer marker (KLK3) were evaluated using Real-Time PCR." (PMID 40388455, 2025). "Additionally, lycopene could alleviate the prostate cancer risk by modulating the growth genes like cyclin-dependent protein kinase 7 (CDK7), B-cell lymphoma 2 (BCL2), epidermal growth factor receptor (EGFR), and insulin-like growth factor 1 (IGF-1) receptor." (PMID 40013157, 2025).